BRCA1 (BRCA1 DNA repair associated)
Diseases named in the same sentence as BRCA1 in open-access papers (continued):
Sharing a sentence is not in itself a finding about the gene and the disease.
breast cancer (continued). "Interestingly, one tumor had a medullary phenotype (on a pre-treatment biopsy), which is much more commonly a feature of BRCA1- than BRCA2-related breast cancer, although both tend to feature a continuous pushing margin." (PMID 18053174, 2007). "In conclusion, our strategy of two-stage linkage mapping, therefore, has allowed us to identify five new putative loci related to breast cancer with moderate values that suggests the existence of genetic heterogeneity among these non-BRCA1/2 breast cancer families." (PMID 17760956, 2007). "Additionally, Real-Time PCR was utilized to determine the expression of BRCA1, PP1α, β and γ in primary human breast tumors and normal breast tissue to identify alterations in the expression of these genes in breast cancer." (PMID 17511879, 2007). "In addition to the high-penetrance genes BRCA1/BRCA2, rare mutations in a number of other genes, such as CHEK2, ATM, BRIP1, and PALB1 predispose to breast cancer, as do more common variants in CASP8 and TGFB1." (PMID 17916242, 2007). "In a meta-analysis of such case-based studies, by age 70 years, in BRCA1 carriers breast cancer risk was 65% (95% CI 51–75%) and ovarian cancer risk was 39% (95% CI 22–51%), and in BRCA2 carriers breast cancer risk was 45% (95% CI 33–54%) and ovarian cancer risk was 11% (95% CI 4.1–18%)." (PMID 17213823, 2007). "Linkage studies in non-BRCA1/2 breast cancer families and segregation analysis in ovarian cancer families suggest that a large fraction of the residual familial risks is due to multiple alleles of moderate to low penetrance rather than additional high penetrance susceptibility genes." (PMID 17342202, 2007). "This suggests that even though some functionally deleterious germ line BACH1 mutations have been observed in breast cancer patients, such mutations are rare and may account for only a very small proportion, if any, of non-BRCA1/2 familial breast cancer." (PMID 16430786, 2006). "Increasing age at first live birth was associated with an increased breast cancer risk among BRCA2 mutation carriers (p trend = 0.002) but not BRCA1 carriers." (PMID 17187672, 2006). "To determine whether increased DNA damage as the result of mutant BRCA1 resulted from decreased repair activity, we used lysates from E2 and RA breast cancer clones in the end-joining assay." (PMID 16417649, 2006). "Previous analyses of French Canadian population have also shown that these recurrent BRCA1 and BRCA2 mutations accounted for about 13% (diagnosis before age 41 years) and 3% (diagnosis before 80 years of age) of breast cancer cases and 8% of ovarian cancer cases." (PMID 16539696, 2006). "Several factors promoting or affecting breast cancer pathogenesis, such as Her2/neu, estrogen and progesterone receptors, E-cadherin, vascular endothelial growth factor, and BRCA1 have been identified and are useful as prognostic indicators or therapeutic targets." (PMID 16584539, 2006). "BRCA1 and BRCA2 are the most important breast cancer susceptibility genes identified to date." (PMID 16417652, 2006). "As patients treated for breast cancer are at particular risk for t-AML, it will be of interest to study whether BRCA1 hypermethylation can identify the patients at increased risk for this complication." (PMID 17047656, 2006). "Indications that BRCA1 methylation is important in hereditary breast cancer have been reported." (PMID 16846527, 2006). "The BRCA1 and BRCA2 genes are the major causes of hereditary breast and ovarian cancer, but the underlying genetic defect remains unresolved in the majority of the families with familial or hereditary breast cancer." (PMID 16539695, 2006).
breast cancer (continued). "We therefore wondered whether ER and RAR coactivator proteins such as CBP might differentially associate with these receptors and regulators of DNA repair such as BRCA1 in human breast cancer cell lines." (PMID 16417649, 2006). "Clinical studies of women with BRCA1 mutations treated with radiation for breast cancer have not demonstrated increased acute or late toxicity." (PMID 16404418, 2006). "Several studies, using a variety of designs, have investigated the effect of parity on breast cancer risk among BRCA1 and BRCA2 mutation carriers, but the results have not been consistent." (PMID 17187672, 2006). "We show that epithelial proliferation in breast tissue from women with BRCA1 and BRCA2 mutations or who are otherwise at high risk is stimulated by oestradiol to the same extent to that in tissue taken from women at population risk of breast cancer." (PMID 16538216, 2006). "The expected number of BRCA1 mutations was also somewhat higher than the observed number among families with at least four cases of breast cancer cases and no ovarian cancer cases (4.11 versus 2)." (PMID 16417652, 2006). "BRCAPRO over-predicted the number of BRCA1 mutations in all categories, but especially among families with at least four breast cancer cases and no ovarian cancer cases (19.40 versus 2)." (PMID 16417652, 2006). "We demonstrate that the Tyrer-Cuzick algorithm effectively predicted breast cancer occurrence in women unaffected at the time of recruitment if they were in a family carrying a BRCA1 or BRCA2 mutation, though not otherwise." (PMID 16507150, 2006). "These therapeutic agents could also be effective for sporadic breast cancers with abnormalities in the BRCA genes, which is, as shown here, a considerably larger proportion of all breast cancer patients than germline BRCA1 or BRCA2 mutation carriers." (PMID 16846527, 2006). "The results of the second part of the study demonstrate that spontaneous abortions do not influence the risk of breast cancer among women with either a BRCA1 or BRCA2 mutation." (PMID 16563180, 2006). "Newer imaging technologies, such as MRI, may offer a better technique for the early diagnosis of breast cancer, especially in BRCA1/2 gene carriers." (PMID 16916448, 2006). "Although earlier estimates suggested that BRCA1 and BRCA2 mutations were responsible for 75% of breast cancer families recent population-based studies indicate that these rates may have been overestimated." (PMID 16764716, 2006). "Carriers of BRCA1 and BRCA2 mutation(s) are also at increased risk for other cancers – in particular, both genes increase the risk of ovarian cancer, while BRCA2 confers greatly increased risks of male breast cancer." (PMID 17018160, 2006). "A significant proportion of breast and/or ovarian cancer families of French Canadian descent harbour specific recurrent mutations in BRCA1 and BRCA2 which confer a significantly increased lifetime risk of developing young age of onset breast cancer and ovarian cancer." (PMID 16539696, 2006). "However, induction of progesterone receptor expression by E2 was impaired in the tissue taken from BRCA1 and BRCA2 carriers compared to that taken from women at population risk of breast cancer." (PMID 16538216, 2006). "We found that miscarriages and therapeutic abortions do not influence the risk of breast cancer in BRCA1 carriers." (PMID 16563180, 2006). "We investigated the effect of the TCF7L2 rs12255372 variant on familial breast cancer (BC) risk by means of TaqMan allelic discrimination, analyzing BRCA1/2 mutation-negative index patients of 592 German BC families and 735 control individuals." (PMID 17109766, 2006).
breast cancer (continued). "We report here that hypermethylation of the BRCA1 gene promoter is found in a considerable proportion of primary sporadic breast carcinomas, that is, 13 of 143 (9.1%), which is in the lower end of previously reported frequencies for this alteration in sporadic breast tumours." (PMID 16846527, 2006). "Epithelial phenotype is associated with breast cancers that express neither ER nor erbB2, a feature that also occurs in BRCA1-mutation carriers." (PMID 15642173, 2005). "BRCA1 and BRCA2 mutations have been detected in quite a low proportion of breast cancer families." (PMID 15642173, 2005). "To date, both genetic and non-genetic factors have been suggested to influence breast cancer risk in BRCA1 and BRCA2 mutation carriers, and many implicate estrogen-induced stimulation as a probable contributor." (PMID 16168130, 2005). "BRCA1 and BRCA2 are the two principal hereditary breast cancer susceptibility genes, and the prevalence of their mutations among Brazilian women is unknown." (PMID 16389418, 2005). "Such compensation of the 1100delC defect in CHEK2 might explain the rather low breast cancer risk associated with the CHEK2 variant, compared to that associated with truncating mutations in BRCA1 or BRCA2." (PMID 15700044, 2005). "Interestingly, prophylactic oophorectomy in BRCA1 and BRCA2 mutation carriers under the age of 40 years causes a 60% reduction in the risk of developing breast cancer." (PMID 16457695, 2005). "We have reported elsewhere that parity is a risk factor for breast cancer in BRCA2 carriers but not in BRCA1 carriers." (PMID 16168130, 2005). "Yet, a substantial proportion of familial breast cancer cases have no identifiable BRCA1/BRCA2 germline mutations, and other, yet unidentified genetic factors underlie these cases." (PMID 15756275, 2005). "The identification of the TSG on 8p is an active research area in many laboratories, and linkage studies in some breast cancer families that do not have BRCA1 and BRCA2 mutations suggest that 8p12-22 is a candidate region." (PMID 16457686, 2005). "The AR exon 1 CAG repeat polymorphism does not appear to have an effect on breast cancer risk in BRCA1 or BRCA2 mutation carriers." (PMID 15743497, 2005). "This caused the identification of a population of breast cancer patients with family history, with or without BRCA1-2 mutation." (PMID 15996267, 2005). "3401delC) in the 75 selected non-BRCA1/BRCA2 breast cancer index cases." (PMID 16280053, 2005). "However, we do know that ovarian suppression (a different form of estrogen suppression) does reduce the incidence of breast cancers in BRCA1 carriers." (PMID 16457695, 2005). "In this study, CPM reduced the risk for contralateral breast cancer in BRCA1 or BRCA2 mutation carriers by 91%, independent of the impact of BPO." (PMID 16052221, 2005). "As an extra control group, we also performed additional IGF1 genotyping on BRCA1-negative women belonging to the South Swedish BRCA1 families with available DNA, who did not have breast cancer at the time of mutation testing." (PMID 15756256, 2005). "After a median of 13.4 years of follow-up, none of the BRCA1/2 germ-line mutation carriers has developed breast cancer." (PMID 16079000, 2005). "The second breast cancer case occurred in a BRCA1 carrier at the age of 41 years." (PMID 16079000, 2005).
breast cancer (continued). "Compensation of the 1100delC defect in CHK2 by CHK1, or any other mechanism, might explain the rather low breast cancer risk associated with the CHEK2 variant, compared to that associated with truncating mutations in BRCA1 or BRCA2." (PMID 15700044, 2005). "In spite of the high prevalence of breast cancer in the Brazilian population, there has not been any systematic study of BRCA1 and BRCA2 mutations among breast cancer patients with a family history of the disease." (PMID 16389418, 2005). "About 5–10% of all breast cancer cases occur in women with a strong family history, and in the Netherlands approximately 25% of these cases may be attributed to the BRCA1 and BRCA2 breast cancer susceptibility gene mutations." (PMID 15199386, 2004). "BRCA1- and BRCA2-associated breast cancer tumours have also been reported to have different pathological characteristics from one another, and also from sporadic and other familial tumours." (PMID 15381934, 2004). "This variant conferred no increased cancer risk among BRCA1/2 carriers or sporadic cases (The CHEK2-Breast Cancer Consortium., 2002)." (PMID 15138485, 2004). "BRCA1 and BRCA2 are the most important susceptibility genes for breast and ovarian cancer, and mutations in these two genes account for >80% of all kindreds with hereditary breast/ovarian cancer and for about 2–3% of breast cancer (BC) cases overall." (PMID 14735197, 2004). "In addition to the breast and ovarian cancer risks, there is evidence that BRCA1 and BRCA2 mutations confer increased risks of other cancers such as prostate cancer and pancreatic cancer." (PMID 15381934, 2004). "Additional studies, particularly of women with a family history of breast cancer who do not carry mutations in the BRCA1 or BRCA2 genes, are warranted." (PMID 15535844, 2004). "A significantly increased risk of breast, prostate, cervical, and non-melanoma skin cancer was recently reported in first-degree relatives of early-onset breast cancer patients from Sweden that tested negative for BRCA1 and BRCA2 mutations." (PMID 15630470, 2004). "Although there are data to suggest that oral contraceptive use is associated with a small increased breast cancer risk in carriers of BRCA1 (but not BRCA2) mutations, this effect was being driven by use prior to the mid 1970s." (PMID 15545966, 2004). "BRCA1 protein products may however have an important role in the development of sporadic breast cancers as shown by transfection studies." (PMID 12698194, 2003). "Interestingly, treatment with the two main marine n-3 fatty acids (EPA and DHA) was shown to increase BRCA1 mRNA expressions in breast cancer cell lines." (PMID 14583770, 2003). "Overexpression of the BRCA1 gene interferes with breast cancer cell growth in vitro and may induce apoptosis if overexpressed in transfected cancer cells, supporting the hypothesis that BRCA1 is a tumour suppressor gene." (PMID 12698198, 2003). "The International Breast Cancer Linkage Consortium data show that, among families with multiple cases of breast cancer but no known ovarian cancers, BRCA1 and BRCA2 mutations are almost equally represented." (PMID 12698193, 2003). "However, it is consistent with the prediction of roughly equal prevalence of BRCA1 and BRCA2 mutations, based on a survey of very early onset breast cancers." (PMID 12698193, 2003). "BRCA1 protein appears to have a significant role in both sporadic and hereditary breast cancers." (PMID 12698194, 2003).
breast cancer (continued). "The results obtained in BRCA1 full-length transfected cells suggest that the BRCA1 gene product is a key modulator of drug sensitivity in breast cancer cells in this specifc setting and add novel information as compared to studies performed on breast sporadic tumours." (PMID 12698198, 2003). "Familial breast carcinomas with germline mutations of BRCA1 are frequently associated with absence of c-erbB-2 expression." (PMID 12698194, 2003). "For the subgroup of young breast cancer patients without a family history and without a BRCA1/2 mutation, mean radiation induced MN yields of 940±165(SD) per 1000 BN for HDR and 472±95(SD) MN per 1000 BN for LDR were obtained." (PMID 12454765, 2002). "We used data from both a population based series of breast cancer cases and high risk families in the UK, with information on BRCA1 and BRCA2 mutation status, to investigate the genetic models that can best explain familial breast cancer outside BRCA1 and BRCA2 families." (PMID 11857015, 2002). "Analysis of the sub-population of young breast cancer patients without family history and without BRCA1/2 mutation revealed that this subgroup is the most radiosensitive for all the different assays (G2 assay: 50%; HDR MN assay: 75%; LDR MN assay: 78%)." (PMID 12454765, 2002). "To estimate more precisely the shape of the incidence curves for BRCA1 and BRCA2 mutation carriers, we fitted a model where separate breast cancer relative risks were assumed for ages 20–39, 40–49, 50–59 and 60–79 years, for both BRCA1 and BRCA2 mutation carriers." (PMID 11857015, 2002). "Six of the BRCA1 mutation carriers did not have any family history of breast or ovarian cancer in first degree relatives and two had a relative diagnosed with breast cancer under age 80 years." (PMID 11857015, 2002). "For the group of young breast cancer patients without a family history and without a BRCA1/2 mutation, the mean radiation-induced yield was 1.24±0.26 (SD) and five out of 10 young breast cancer patients had G2 values higher than the cut-off value." (PMID 12454765, 2002). "In conclusion, the present results suggest that a number of low penetrant genes may account for the familial clustering of breast cancer outside BRCA1 and BRCA2 families." (PMID 11857015, 2002). "Future studies will be focused on the group of breast cancer patients with a BRCA1/2 mutation and young breast cancer patients without a family history." (PMID 12454765, 2002). "This was due to the absence of family history of breast cancer in BRCA1 mutation carriers in the ABC families." (PMID 11857015, 2002). "The modifying effect on the breast cancer risks of BRCA1 and BRCA2 carriers may explain some of the differences between the risk estimates from population based studies and high risk families." (PMID 11857015, 2002). "In computing the probability that a woman is a BRCA1 or BRCA2 carrier for genetic counselling purposes, it is important to allow for the fact that other breast cancer susceptibility genes may exist." (PMID 11857015, 2002). "We conclude that bilaterality of breast cancer on its own is not strongly associated with BRCA1 and BRCA2 mutations when adjusted for age and family history." (PMID 11556836, 2001). "We conclude that the features of BRCA1 associated tumours detected in a hospital-based series of breast cancer patients not selected for family history of age at diagnosis are similar to tumours in cases selected for family history or age at diagnosis." (PMID 11720473, 2001). "As CHK2 has been found to bind and regulate BRCA1, the product of one of the 2 known major susceptibility genes to hereditary breast cancer, it also more directly makes CHK2 a suitable candidate gene for hereditary predisposition to breast cancer." (PMID 11461078, 2001).